OR10AD1 (olfactory receptor family 10 subfamily AD member 1)
Description:
Odorant receptor.
Synonyms: OR10AD1P; OR12-1
Tractability: Antibody: UniProt places it where antibodies can reach, with medium confidence; UniProt predicts a signal peptide or a membrane-spanning region; its Gene Ontology location is reachable by antibodies, with medium confidence.
Gene: Protein-coding gene on chromosome 12 (48,202,339 to 48,203,292, reverse strand). Ensembl gene ENSG00000172640.
Subcellular location: Cell membrane
Pathways (Reactome):
Sensory Perception: Expression and translocation of olfactory receptors
Gene Ontology:
Molecular function: olfactory receptor activity; G protein-coupled receptor activity
Biological process: detection of chemical stimulus involved in sensory perception of smell; G protein-coupled receptor signaling pathway
Cellular component: plasma membrane; membrane
Homologues: Orthologues: rat Or10ad1 (81% identical), mouse Or10ad1 (80% identical), mouse Or10ad1b (80% identical), rat Olr1102 (80% identical), mouse Or10ad1c (79% identical), rat Olr1877 (79% identical), guinea pig OR10AD1 (59% identical). Paralogues in human: OR10A4 (44% identical), OR10A5 (43% identical), OR10C1 (43% identical), OR5V1 (42% identical), OR10A2 (42% identical), OR10A7 (42% identical), OR13C4 (42% identical), OR2F1 (42% identical), OR13C9 (41% identical), OR2D3 (41% identical), OR6B1 (41% identical), OR2D2 (41% identical), and 80 more.